TNF (tumor necrosis factor)
Diseases named in the same sentence as TNF in open-access papers (continued):
Sharing a sentence is not in itself a finding about the gene and the disease.
diabetes (continued). "In individuals with periodontitis and type 2 diabetes, serum concentrations of TNF-α and IL-10 were higher in patients with diabetes and IL-10 levels were strongly correlated with the severity of periodontal disease." (PMID 28906456, 2017). "Tumor necrosis factor- (TNF-) related apoptosis-inducing ligand (TRAIL) is attracting attention for its role in the physiopathology of metabolic disease/diabetes." (PMID 29056829, 2017). "Increased TNF-α and interleukine-6 (IL-6) levels through metabolic control exist in types 1 and 2 diabetic patients, which suggest that the control of diabetes improves the capacity of activation and maintenance of these pro-inflammatory cytokines." (PMID 28426801, 2017). "The role of TNF-α in the development of diabetes and diabetic complications warrant future investigation." (PMID 28426801, 2017). "Diabetes induces intestinal iNOS expression, plasma NO levels in the portal vein, IL-1β and TNF-α expression of Kupffer cells, and K. pneumonia loads in the liver." (PMID 28493939, 2017). "As observed in our results, β-glucan treatment decreased both TNF-α blood levels in animals with periodontal disease and diabetes and IL-10 levels in animals with periodontal disease." (PMID 28906456, 2017). "Increase in ROS can activate pro-inflammatory chemokines, tumor necrosis factor (TNF-α), macrophage chemotactic proteins (MCP-1), and interleukins (IL-1β and 6) that have been implicated in the progression of diabetes to diabetic complications." (PMID 28497094, 2017). "The aim of this study is to investigate the effect of maternal diabetes on adipocytokines (adiponectin, leptin and TNF-α) production in F1 offspring in rats." (PMID 28078101, 2017). "The aim of this study was used meta-analysis to investigate changes of serum tumor necrosis factor-alpha (TNF-α) in patients with type 1 diabetes mellitus (T1DM)." (PMID 28426801, 2017). "It was previously reported that inflammatory responses such as IL-6 and TNF-α accumulated oxidative damage products in the liver of diabetes mellitus (DM) patients." (PMID 28811499, 2017). "Inhibition of TNF-α with a neutralizing antibody reduced the features of DN in both type 1 and type 2 diabetes mellitus." (PMID 28881810, 2017). "Our results showed that IFX, a TNF-α antagonist, decreased alveolar bone loss and expression levels of osteocytic RANKL and sclerostin in STZ-induced diabetes rats with periodontitis." (PMID 29240821, 2017). "In this study, IL-18, TNF- α and IL-6 had positive correlation with the degree of diabetes control and is similar to what had been observed in other studies." (PMID 28577020, 2017). "At the same time, the inflammatory infiltration of macrophages was significantly increased and pro-inflammatory cytokine such as MCP-1 and TNF-α mRNA and protein expression were also markedly elevated in diabetic liver." (PMID 29078720, 2017). "Serum TNF-α level is elevated in type 1 and type 2 diabetic patients and is correlated with various complications of diabetes." (PMID 28078101, 2017). "The elevated levels of inflammatory markers, including C-reactive protein (CRP), tumor necrosis factor alpha (TNF-α), and interleukin 6 (IL6) are supposed to be associated with type 2 diabetes mellitus (T2DM)." (PMID 28716139, 2017). "For example, TNFα has been shown to modulate diabetes, EAE, lupus and arthritis in animal models, possibly, by inhibiting Th17 cells." (PMID 28488248, 2017). "During pre-diabetes, myocardia are exposed to a variety of risk factors such as elevated levels of FFA and inflammatory factors, TNF-α, IL-1β, and CRP." (PMID 28304381, 2017). "It was evaluated in untreated islets as well as islets pretreated with high glucose and TNF-alpha in order to stimulate hyperglycaemic and inflammatory stress as apparent during diabetes mellitus type 2." (PMID 28542222, 2017).
diabetes (continued). "Our group found that through NF-κB inhibition, P. hepiali suppressed the release of proinflammatory cytokines, including tumor necrosis factor alpha, IL-2, IL-6 and IL-10, in a rat model of diabetes induced by a high-fat diet and STZ." (PMID 28662169, 2017). "Clinical efficacy of abatacept has been reported in patients with active RA, including those with an inadequate response to MTX or TNF inhibitors, in early type 1 diabetes mellitus, and more recently, in primary Sjögren’s syndrome." (PMID 28679449, 2017). "The diabetes + IR group had significantly (p < 0.001) high levels of TNF-α and IL-6 as compared to the diabetic-control group." (PMID 28505121, 2017). "In patients who are obese and who have diabetes, tumor necrosis factor-α (TNF-α) can induce an increase in PTX3 in smooth muscle cells (HASMC) through the MAPK pathway in response to inflammation." (PMID 28770376, 2017). "TNF-α is one of the major cytokines responsible for chronic inflammation in diabetes, and plays a pivotal role in the development of renal and retinal microvascular complications." (PMID 29240802, 2017). "Patients with diabetes have increased circulating levels of inflammatory markers including tumor necrosis factor-α (TNF-α), interleukin-6 (IL-6), and chemokine (C–C motif) ligand 2 (CCL2)." (PMID 26861446, 2016). "Both the mRNA and the protein levels of TNF-α, IL-1β, and iNOS were elevated after 4 weeks of diabetes." (PMID 27143993, 2016). "In diabetes, both intrinsic (mitochondrial cytochrome c mediated) and extrinsic (death receptors like Fas or TNF α mediated) apoptosis are reported to be augmented and FOXO1 is suggested to increase the expression of caspases and cell death receptors." (PMID 26956801, 2016). "What’s more, ZER significantly (p < 0.05) ameliorated diabetes-induced upregulation of tumor necrosis factor-α, interleukin (IL)-1 and IL-6." (PMID 27463726, 2016). "For instance, patients with type 2 diabetes mellitus and hypertension show severe increase of serum TNF-α, which is significantly attenuated by acetylsalicylic acid." (PMID 27562094, 2016). "Similar to the effects observed in healthy participants, studies in individuals with diabetes that measured TNFα found that the high AGE intervention resulted in significantly higher circulating levels." (PMID 26938557, 2016). "We have previously shown that diabetes is associated with increased production of PGE2, IL-6 and TNF-α in macrophages." (PMID 27351842, 2016). "This is consistent with the impaired wound healing of diabetic foot ulcers by diabetes-enhanced elevated or prolonged expression of TNFα in diabetic patients." (PMID 26973819, 2016). "When multiple regression models were used, diabetes remained significantly associated with NETs, nucleosomes, HNE-DNA complexes, IL-6 and TNFα after adjustment for BMI." (PMID 28005949, 2016). "Elevated levels of plasma CRP have been reported to enhance the development of diabetes by interacting with cytokines (IL-6 and TNF-α) in stimulating the acute phase inflammatory response." (PMID 27379252, 2016). "Both plasma and vitreous TNF-α levels are elevated in patients with diabetes, and plasma TNF-α levels are correlated with DR severity." (PMID 27618014, 2016). "Several studies revealed increases in TNF-α, resistin, and visfatin levels in various disorders such as cholelithiasis, diabetes, and atherosclerosis." (PMID 28018676, 2016). "A study demonstrates that management of diabetes with morin reduced the elevation of inflammatory cytokines IL-1β, IL-6 and TNF-α via a SphK1/S1P signaling pathway." (PMID 27527213, 2016). "Hyperlipidemia and hyperglycaemia in diabetes induces transcription of proinflammatory cytokines, tumour necrosis factor alpha (TNF‐α) and monocyte chemotactic protein‐1 (MCP‐1)." (PMID 26645107, 2016). "TNF-α was elevated after diabetes induction (53 % in ET2D, p = 0.084; and 177 % in L-T2D, p < 0.001) as compared to controls." (PMID 26877773, 2016).
diabetes (continued). "Metformin administration has also been shown to downregulate the expression of NFkβ and TNFα and ameliorate β-cell dysfunction in diabetes." (PMID 27551311, 2016). "Types 1 and 2 diabetes have been related to elevated levels of inflammatory mediators, such as IL-1β and TNF- α." (PMID 28074077, 2016). "ExT has been shown to normalize diabetes-related elevations in blood glucose, plasma Ang II, and TNF-α." (PMID 26989452, 2016). "Our experiments showed that the presence of diabetes led to elevated expression of TNF-α, IL-6 and p-NFκB in tumor tissues." (PMID 27413117, 2016). "It is reported that there is a relationship between TNF-α increase in diabetes and impairment of insulin signaling pathway by increasing serine phosphorylation of IRS-1 which inhibits IR tyrosine kinase activity and leads to downstream signaling." (PMID 27579151, 2016). "TNF-α has been suggested to participate in the development of diabetes by impairing insulin actions." (PMID 27013528, 2016). "SASP genes (i.e., IL-1α, IL-1β, IL-6, and TNF-α) are chronically activated in cells and tissues from diabetes patients." (PMID 27340505, 2016). "Western blot results showed that diabetes resulted in significantly elevated TNF-α, IL-6 and p-NFκB expression in primary and metastatic tumors, while SB203580 treatment markedly reduced their expression." (PMID 27413117, 2016). "Of importance, endothelial dysfunction evoked by TNF-α is reduced in fit and well-controlled type 1 diabetes mellitus patients." (PMID 27562094, 2016). "Experimental studies in animal models of diabetes have showed that TNF-α protein and expression levels are enhanced in renal glomeruli and tubules." (PMID 25785280, 2015). "We found that pioglitazone and resveratrol significantly suppressed liver TNF-α and IL-1β levels in Balb/C mice with MG-induced diabetes." (PMID 25884658, 2015). "CTRP9 downregulation by TNF-α-initiated oxidative PPARγ suppression contributes to the exacerbated heart injury in diabetes." (PMID 26457306, 2015). "C-reactive protein (CRP), tumor necrosis factor- (TNF-α) and interleukin-6 (IL-6) are mediators widely described in worldwide literature have been associated with depression, MCI and diabetes." (PMID 25793613, 2015). "Contradictory results were reported from studies of TNF-α levels in oral fluids among patients with diabetes and chronic periodontitis." (PMID 26211001, 2015). "The increased ROS is also a great inducer for the release of TNF-α promoting to endothelial dysfunction in diabetes." (PMID 25950001, 2015). "Patients with diabetes and periodontal disease had significantly higher mean levels of serum TNF-α, IL-6 and CRP than healthy subjects (P < 0.001)." (PMID 26644840, 2015). "Measurements of blood TNF-α levels in rats with diabetes and ischemia showed that TNF-α increased with elapsed time after ischemia in the non-DM group." (PMID 26665003, 2015). "Zinc appears to be involved in the reduction or delay in the onset of diabetes by decreasing TNFα and IL-1, cytokines known for their role in beta-cell destruction." (PMID 26043030, 2015). "In diabetes, oxidative stress increases the excretion of inflammation-related cytokines, such as IL-6 and TNF-α." (PMID 26176625, 2015). "Overexpression of heparanase in diabetic mouse models increased TNF-α expression in kidney tissue and activated kidney-damaging macrophages, whereas heparanase knockout mice with diabetes demonstrated reduced albuminuria." (PMID 26064987, 2015). "Patients with diabetes and periodontal disease had significantly higher mean levels of serum TNF-α (1.79 ± 0.19 vs 0.82 ± 0.17 pg/mL), IL-6 (0.57 ± 0.07 vs 0.38 ± 0.05 pg/mL), and CRP (0.39 ± 0.11 vs 0.21 ± 0.08 mg/L) by comparison with healthy subjects." (PMID 26644840, 2015). "In fact, in our previous study, increased expression of TNF-α was observed in the rat periodontium after diabetes induction." (PMID 26270535, 2015).
diabetes (continued). "PATs from SENP1-aP2KO mice expressed high levels of IL-6, TNF-α and IL-1β at the age of 7 weeks before the onset of diabetes, and these proinflammatory cytokines were higher in the PATs compared with other adipose depots." (PMID 26596471, 2015). "Expression of proinflammatory parameters including tumor necrosis factor-α and vascular endothelial growth factor was significantly inhibited in green tea-treated retina as compared to diabetic retina." (PMID 26539551, 2015). "In the current study, comparison of water treatment to green tea treatment in diabetic rats revealed that the green tea-treated subgroup had fewer TNF-α-positive cells than the water-treated subgroup at 60 and 90 days after diabetes induction." (PMID 26270535, 2015). "Studies in human diabetic individuals revealed that hyperglycaemia acutely increases circulating cytokine concentrations of IL-6 and TNF-α by an oxidative mechanism, and plays a role in immune activation in diabetes." (PMID 25923079, 2015). "Data from animal models documented that TNF-α was downregulated in the dorsal root ganglion in early stages of experimental diabetes, while the opposite occurred in later stages." (PMID 25961054, 2015). "Circulating IL-6 and TNF-α were markedly different among these groups with a tendency of increment in accordance with the emergence of diabetes and diabetic microangiopathy (P < 0.05 or P < 0.01)." (PMID 26106251, 2015). "Serum levels of TNF-α and IL-6 were measured by enzyme-linked immunosorbent assay and CRP by nephelometry by using the proper commercial kits in 30 patients with diabetes and periodontal disease, and also in a control group of 30 healthy subjects." (PMID 26644840, 2015). "Circulating markers of inflammation include C-reactive protein (CRP), interleukin-6 (IL-6), fibrinogen, and tumor necrosis factor-alpha (TNF-α), some of which have been associated with cognitive dysfunction in people with diabetes." (PMID 26060511, 2015). "Key words:Melatonin, periodontal disease, diabetes mellitus, interleukin-6, tumor necrosis factor-alpha, C-reactive protein, inflammatory markers." (PMID 26644840, 2015). "EMCV-induced diabetes in mice is attenuated by daily injection of neutralizing antibodies against the cytokines interleukin-1 (IL-1β) or tumor necrosis factor (TNF-α), or administration of aminoguanidine, a selective iNOS inhibitor." (PMID 26295266, 2015). "IL-18 and TNF-α levels also correlated positively with the degree of albuminuria in the patients with diabetes." (PMID 26064987, 2015). "In the diabetes + β-anhydroicaritin group, the expression of TNF-α was weakly positive in the gingival epithelium and fibroblasts." (PMID 25847066, 2015). "TNF-α altered retinal vascular permeability in diabetes through down-regulation of ZO-1 and claudin-5 protein and mRNA, which is mediated by NF-κB activation." (PMID 25617421, 2015). "There is a significant elevation in the interleukin-6 (IL-6), C-reactive protein (CRP), tumour necrosis factor-alpha (TNF-α) and IL-1β levels in preclinical diabetes samples." (PMID 26596471, 2015). "Our study also indicated that the treatment of chelerythrine downregulated CD36 and IL-1β as well as inflammation related genes like IFNγ and TNFα, which are of great benefits for the treatment of diabetes." (PMID 26183621, 2015). "Sesamol attenuated TNF-α levels in STZ induced diabetes in rats and in our study also elevated levels of TNF- α were significantly attenuated (p < 0.001) by S-SLN treatment and the effect was significantly (p < 0.001) better than FS group." (PMID 25935744, 2015). "Because diabetes can affect the expressions of many cytokines related to immunity and inflammation, we examined uterine expressions of tumor necrosis factor α (TNFα) and interleukin 1β (IL-1β)." (PMID 26002932, 2015). "The gene expression of Homer1, Homer2, Homer3, IL-1β, and TNF-α were analyzed by hypertension and diabetes between CAD patients and controls." (PMID 25551602, 2014).
diabetes (continued). "Specifically, inflammatory cytokines such as interleukins IL-6, IL-2, and tumor necrosis factor-α (TNF-α) are elevated in hyperglycemia, suggesting that a chronic low grade inflammatory state exists in patients with diabetes." (PMID 24961298, 2014). "Previous reports have shown that urinary MCP‐1 and TNF‐α excretion increases in patients with diabetes, and the increment is even greater when albuminuria is severe." (PMID 24744899, 2014). "It is important to realize that modification of TNF-α activity in type 1 diabetes mellitus should be undertaken in complication-free phase of the disease." (PMID 25053869, 2014). "Diabetes-induced changes in growth factor binding protein 3 (IGFBP-3) and tumor necrosis factor alpha (TNFα) have been linked to decreased insulin receptor signaling in diabetic retinopathy." (PMID 24695399, 2014). "We found that diabetes enhances the production of O2−, activates caspase-3, and induces the expression of proinflammatory cytokines (TNF-α and IL-1β) in the brain." (PMID 24739976, 2014). "We have previously reported that another protein, IGFBP-3, is reduced in response to diabetes, in correlation with the observed increase in TNFα." (PMID 25073020, 2014). "Inflammation generally and TNF-α in particular is elevated in inflammatory conditions including diabetes and contributes to diabetic complications in mineralized tissues." (PMID 24971753, 2014). "Evidently, it has been reported that diabetes apart from presenting an altered metabolic condition, results from a perturbed immune regulation instigating inflammatory cytokines, e.g. TNF-α." (PMID 25501750, 2014). "The transcription and expression of inflammatory factors, including TNF-α and IL-6, are activated in patients with type 2 diabetes mellitus." (PMID 25187806, 2014). "Overall, the inflammatory parameters (neutrophil accumulation - myeloperoxidase activity, tumor necrosis factor alpha, and monocyte chemotactic protein-1 levels and mast cell counting) increased in subcutaneous implants after diabetes induction." (PMID 25372281, 2014). "Diabetes-induced over-expression of inflammatory factors, such as TNF-α, is known to play important roles in DR." (PMID 25271989, 2014). "TNFα expression was also highly increased in the Ren2 rat retina, and diabetes mellitus further upregulated this." (PMID 24968134, 2014). "Inflammation, reactive oxygen species (ROS) and TNF-α levels are elevated in diabetes and enhance FOXO1/β-catenin interactions at the expense of TCF/LEF-dependent transcription." (PMID 24971753, 2014). "In donors with diabetes, basal Ca2+ was lower inititially and was increased by TNF from 60±2 nM to 70±3 nM (p<0.001)." (PMID 24466329, 2014). "Puerarin at 20 and 100 nM decreased the diabetes-induced elevation of TNF-α, IL-1β, and IL-6 (P < 0.001) and NF-κB DNA binding activities (P < 0.01 and P < 0.001 at 20 nM and 100 nM, resp.)." (PMID 25089076, 2014). "Our results clearly indicate that diabetes leads to increased IL-1β and TNF-α immunoreactivity in the kidney." (PMID 24817793, 2014). "Diabetes is considered as a kind of inflammatory and metabolic diseases, so the overproduction of IL-6, TNF-α, and IL-1β has been observed in people with diabetes." (PMID 24995360, 2014). "In the Insulin Resistance Atherosclerosis Study, circulating levels of TNF-α were elevated in individuals with impaired glucose tolerance and type 2 diabetes mellitus." (PMID 25105150, 2014). "In our findings, TNF-α levels and the apoptotic index were also higher in the internal fibrovascular tissue in diabetes." (PMID 25372281, 2014). "In this context, lipopolysaccharides can aggravate diabetes through an increased production of IL-1β, TNF-α and PGE2." (PMID 24121926, 2014). "TNFα, TNFR1 and TNFR2 were each significantly associated with at least two of the following: age, estimated glomerular filtration rate, hypertension, diabetes, smoking, peripheral vascular disease or history of atrial fibrillation." (PMID 24923671, 2014).